ARAP1 (ArfGAP with RhoGAP domain, ankyrin repeat and PH domain 1)
Description:
Phosphatidylinositol 3,4,5-trisphosphate-dependent GTPase-activating protein that modulates actin cytoskeleton remodeling by regulating ARF and RHO family members. Activated by phosphatidylinositol 3,4,5-trisphosphate (PtdIns(3,4,5)P3) binding and, to a lesser extent, by phosphatidylinositol 3,4-bisphosphate (PtdIns(3,4)P2) binding. Has a preference for ARF1 and ARF5. Positively regulates the ring size of circular dorsal ruffles and promotes macropinocytosis. Acts as a bridging factor in osteoclasts to control actin and membrane dynamics (By similarity). Regulates the condensing of osteoclast podosomes into sealing zones which segregate the bone-facing membrane from other membrane domains and are required for osteoclast resorption activity (By similarity). Also regulates recruitment of the AP-3 complex to endosomal membranes and trafficking of lysosomal membrane proteins to the ruffled membrane border of osteoclasts to modulate bone resorption (By similarity). Regulates the endocytic trafficking of EGFR. Regulates the incorporation of CD63 and CD9 into multivesicular bodies. Required in the retinal pigment epithelium (RPE) for photoreceptor survival due to its role in promoting RPE phagocytosis (By similarity).
Synonyms: Cnt-d2; CENTD2
Tractability: Antibody: UniProt places it where antibodies can reach, with high confidence; its Gene Ontology location is reachable by antibodies, with high confidence; the Human Protein Atlas places it where antibodies can reach. PROTAC: ubiquitination databases record sites on it; its protein half-life has been measured.
Gene: Protein-coding gene on chromosome 11 (72,683,204 to 72,793,599, reverse strand). Ensembl gene ENSG00000186635.
Subcellular location: Cytoplasm; Golgi apparatus, trans-Golgi network; Golgi apparatus, Golgi stack; Cell membrane; Endosome, multivesicular body; Cell projection, ruffle; Cell projection, podosome; Early endosome
Subcellular location (Human Protein Atlas): Nucleoplasm; Plasma membrane; Cytosol; Vesicles
Pathways (Reactome):
Signal Transduction: CDC42 GTPase cycle; PTK6 Regulates RTKs and Their Effectors AKT1 and DOK1; RAC1 GTPase cycle; RHOA GTPase cycle
Gene Ontology:
Molecular function: GTPase activator activity; phosphatidylinositol-3,4,5-trisphosphate binding; protein binding; type 1 angiotensin receptor binding
Biological process: negative regulation of stress fiber assembly; positive regulation of filopodium assembly; positive regulation of GTPase activity; regulation of cell shape; regulation of receptor internalization; actin filament organization; photoreceptor cell maintenance; positive regulation of phagocytosis; regulation of actin cytoskeleton organization; regulation of bone resorption; regulation of cell projection organization; regulation of small GTPase mediated signal transduction; positive regulation of cellular component organization; positive regulation of receptor recycling; regulation of endocytosis; signal transduction
Cellular component: cytoplasm; extrinsic component of plasma membrane; Golgi apparatus; multivesicular body; plasma membrane; cytosol; early endosome; podosome; trans-Golgi network; endosome; Golgi stack; ruffle
Genetic constraint (gnomAD): Loss-of-function variants: 76 observed, 160.76 expected, observed/expected ratio (o/e) 0.47, 90% interval 0.39 to 0.57. The upper end of that interval is the gene's LOEUF score, 0.57, which puts it in group 2 of 6, group 1 being the genes least tolerant of losing a copy. Missense variants: 1,686 observed, 1,910.4 expected, observed/expected ratio (o/e) 0.88, 90% interval 0.85 to 0.92. Synonymous variants: 804 observed, 781.83 expected, observed/expected ratio (o/e) 1.03, 90% interval 0.97 to 1.09.
Homologues: Orthologues: macaque ARAP1 (97% identical), chimpanzee ARAP1 (97% identical), pig ARAP1 (92% identical), dog ARAP1 (92% identical), mouse Arap1 (90% identical), rat Arap1 (90% identical), guinea pig ARAP1 (90% identical). Paralogues in human: ARAP2 (37% identical), ARAP3 (33% identical), ASAP2 (13% identical), ASAP1 (12% identical), ASAP3 (10% identical), ACAP3 (10% identical), ACAP1 (9% identical), ACAP2 (9% identical), AGAP2 (8% identical), AGAP1 (8% identical), AGAP3 (8% identical), GIT2 (8% identical), and 16 more.
Diseases named in the same sentence as ARAP1 in open-access papers:
ARAP1 is named in the same sentence as 18 diseases in open-access papers, as found by Europe PMC text mining. Sharing a sentence is not in itself a finding about the gene and the disease. The quoted sentences say what the papers report.
type 2 diabetes (13 papers, 2011 to 2025). "While previous research has linked ARAP1 polymorphisms to an elevated risk of type 2 diabetes, its specific contribution to GDM, especially in younger populations, remains underexplored." (PMID 41036138, 2025). "The risk allele (C) of STARD10 rs11603334 for type 2 diabetes is positioned near the ARAP1 promoter." (PMID 41036138, 2025). "Genome‐wide association studies (GWAS) have reported that the 11q13.4 locus near ARAP1 is significantly associated with type 2 diabetes." (PMID 32969198, 2020). "ARAP1, single nucleotide polymorphisms (rs1552224 and rs11603334) in which were confirmed to increase type 2 diabetes susceptibility, connects phosphatidyl inositol 3 phosphate (PIP3) and phosphotyrosine signalling and the Arf and Rho signalling pathways." (PMID 32969198, 2020). "The ArfGAP with RhoGAP domain, ankyrin repeat, and PH domain-containing protein 1 (ARAP1) rs1552224 locus has been identified as a risk locus for type 2 diabetes, and recent reports have linked it to elevated blood glucose levels and reduced insulin release upon glucose stimulation." (PMID 41036138, 2025). "CENTD2 (also known as ARAP1) was initially identified as significantly associated with type 2 diabetes susceptibility, and its risk allele was associated with reduced insulin beta-cell function in nondiabetic subjects, in populations of European descent in 2010." (PMID 25587982, 2015). "In addition, ARAP1 is known as a common regulatory variant for type 2 diabetes in humans." (PMID 36611792, 2023). "Of these, only ARAP1 and BRD7 were affected by globally significant SNPs (i.e., rs8050136 and rs11603334) that had previously been associated with both obesity and type 2 diabetes." (PMID 29081791, 2017). "We show that the known loci for HbA1c, such as ABCB11, and the established type 2 diabetes loci, IGF2BP2, and ARAP1, could mediate their effect on type 2 diabetes risk by their action on pancreatic beta-cell glucose sensitivity." (PMID 32944759, 2021).
diabetes (6 papers, 2012 to 2025). "Among candidate loci, the macrophage migration inhibitory factor (MIF) gene and the ARAP1 locus have been implicated in diabetes-related traits." (PMID 41036138, 2025). "Findings suggest that ARAP1 engages in islet insulin content and secretion and is thus likely to mediate the effects on diabetes susceptibility." (PMID 35399945, 2022). "Similarly, the two strongest weighted loci in Cluster 2 are ARAP1, a locus at which diabetes risk is thought to be mediated by modulation of STARD10 expression in pancreatic beta cells, and SPRY2, a locus at which the closest gene, SPRY2, regulates insulin transcription." (PMID 30240442, 2018). "Novel variants in the genes ARAP1, GLIS3, MADD, NOTCH2 and WFS1 need further investigation to reveal their possible role in diabetes." (PMID 22662265, 2012).
Insulin resistance (4 papers, 2017 to 2024). Increased resistance towards insulin, that is, diminished effectiveness of insulin in reducing blood glucose levels. "Given the existence of insulin resistance in global StarD10 mice, likely to be the result of changes in liver function, we reassessed the impact of variants near ARAP1 and STARD10 on this parameter in humans by consulting previously published data." (PMID 28132686, 2017).
Sepsis (4 papers, 2013 to 2024). Sepsis is defined as life-threatening organ dysfunction caused by a dysregulated host response to infection. "During endotoxemia, Arap1 expression is markedly down-regulated and sepsis-induced circulatory failure is aggravated in Arap1-deficient mice." (PMID 23844607, 2013). "Our data suggest that down-regulation of Arap1 expression during sepsis contributes to the development of hypotension by causing reduced vascular sensitivity to angiotensin II." (PMID 23844607, 2013). "In the present study, we used Arap1-deficient mice to investigate the possible involvement of Arap1 in sepsis-induced hypotension." (PMID 23844607, 2013). "In the present study, we used Arap1-deficient mice to address the hypothesis that Arap1 might be involved in the vasculature's loss of sensitivity to angiotensin II during sepsis." (PMID 23844607, 2013). "Arap1-deficient mice were used to assess the role of Arap1 in sepsis-induced hypotension." (PMID 23844607, 2013). "• Arap1 deficiency aggravates sepsis-induced circulatory failure." (PMID 23844607, 2013). "The blood pressure homeostasis during endotoxemia was more severely compromised in Arap1-deficient mice than in wildtypes, suggesting that down-regulation of Arap1 expression during the course of sepsis may contribute to the development of hyporeactivity to angiotensin II." (PMID 23844607, 2013). "In an endotoxaemic mouse model, Arap1 was markedly downregulated by sepsis, and sepsis-induced circulatory failure worsened in Arap1-deficient mice." (PMID 25673430, 2014). "In fact, the Arap1 expression in several organs declined during the course of the experimental sepsis, reaching levels below 10% of the baseline." (PMID 23844607, 2013). "We found that during lipopolysaccharide (LPS)-induced sepsis in mice, Arap1 expression was markedly down-regulated; Arap1 expression was similarly reduced in cultured cells in the presence of pro-inflammatory cytokines." (PMID 23844607, 2013). "During endotoxemia, mean arterial blood pressure (MAP) decreased in both genotypes, with the time course of sepsis-induced hypotension being markedly accelerated in Arap1-/- compared to +/+ mice." (PMID 23844607, 2013). "During endotoxemia-induced sepsis, the blood pressure of Arap1-/- and wildtype mice was measured for seven hours after a single LPS (3 mg/kg) injection using radio-telemetry (n = 10 each)." (PMID 23844607, 2013). "Furthermore, experimental endotoxemia in Arap1 knockout mice suggests that the downregulation of ARAP1 expression during sepsis contributes to the development of hypotension by reducing vascular sensitivity to angiotensin II." (PMID 38877367, 2024). "In addition, we also recently reported down-regulation of ANGPTL2/Arap1 function in sepsis-induced hypotension due to reduced AT1A receptor recycling in vascular cells." (PMID 27677409, 2016). "The virtual loss of Arap1 during endotoxemia would reduce the surface expression of the AT1 receptor in the vasculature and would contribute to the hyporesponsiveness to angiotensin II observed during sepsis." (PMID 23844607, 2013). "We hypothesized that changes in Arap1 expression under septic conditions may contribute to the blunted vascular sensitivity to angiotensin II during sepsis." (PMID 23844607, 2013). "We hypothesized that a dysregulation of Arap1 expression during sepsis may be involved in the hyporeactivity of vascular AT1 receptors, contributing to a decrease in the total vascular resistance." (PMID 23844607, 2013). "Thus, angiotensin II in combination with pro-inflammatory cytokines likely accounts for the down-regulation of Arap1 during LPS-induced sepsis." (PMID 23844607, 2013). "Therefore, we hypothesized that Arap1-dependent modulation of the AT1 receptor may contribute to angiotensin resistance during sepsis." (PMID 23844607, 2013).
Sepsis (continued). "Thus, the reduced Arap1 expression during sepsis may be mediated by pro-inflammatory cytokines, all of which are known to be markedly elevated during endotoxemia." (PMID 23844607, 2013). "Because of the MAP differences between the Arap1-/- and +/+ mice, we assessed the impact of RAS activation on blood pressure regulation during sepsis-induced hypotension." (PMID 23844607, 2013).
endotoxemia (2 papers, 2013 to 2024). "In summary, during endotoxemia the blood pressure homeostasis in the Arap1-deficient mice was more severely compromised than in wildtype mice." (PMID 23844607, 2013). "It should be noted that the Arap1 expression at this time point was only slightly reduced when compared with the expression during the later course of endotoxemia." (PMID 23844607, 2013). "The endotoxemia-related decline in Arap1 expression could be recapitulated in cultured mesangial cells by incubation with pro-inflammatory cytokines, such as tumor necrosis factor α and interferon γ." (PMID 23844607, 2013). "In contrast to the baseline conditions, when the MAP was maintained in the Arap1-/- mice, the fall in blood pressure after the induction of endotoxemia was more pronounced in the Arap1-/- than in the wildtype mice, at least before the minimum values were reached after approximately six hours." (PMID 23844607, 2013). "We hypothesized that dysregulation of Arap1 may contribute to vascular hyporeactivity to angiotensin II during endotoxemia." (PMID 23844607, 2013). "• In endotoxemia, Arap1 expression is markedly down-regulated." (PMID 23844607, 2013). "Thus, despite the marked blood pressure differences between the Arap1+/+ and -/- mice during the early time course of endotoxemia, blood pressure was indistinguishable between the genotypes when the blood pressure nadir was reached, approximately six hours after the LPS administration." (PMID 23844607, 2013).
lung adenocarcinoma (2 papers, 2009 to 2023). A carcinoma that arises from the lung and is characterized by the presence of malignant glandular epithelial cells. "Moreover, metastatic assays showed that overexpression of ARAP1 significantly inhibits metastasis of lung adenocarcinoma in vitro and in vivo." (PMID 38008882, 2023). "In summary, this study indicates that ARAP1 may serve as a potential prognostic predictor and a metastatic suppressor in lung adenocarcinoma via its RhoGAP activity." (PMID 38008882, 2023). "qPCR and western blot verified that ARAP1 is frequently downregulated in lung adenocarcinoma tumor tissues and cancer cells, and its downregulation might be mediated by epigenetic modification." (PMID 38008882, 2023).
gestational diabetes mellitus (1 paper, 2025). "Moreover, our findings indicate that the ARAP1 rs1552224 variant, specifically the AC genotype and C allele, confers a decreased risk of developing gestational diabetes mellitus (GDM)." (PMID 41036138, 2025).
Hypertension (1 paper, 2023). The presence of chronic increased pressure in the systemic arterial system. "Moreover, at the renal level, overexpression of ARAP1 in mice causes hypertension and renal hypertrophy, effects that are suppressed by an ARB, suggesting that ARAP1 potentiates AT1 receptor signaling." (PMID 37513355, 2023).
renal fibrosis (1 paper, 2023). A final common manifestation of a wide variety of chronic kidney diseases characterized by glomerulosclerosis and tubulointerstitial fibrosis. "The overall results indicated that ARAP1 inhibition was highly effective in limiting renal fibrosis and aberrant glycolysis by reducing the PKM2 dimer expression and subsequent HIF-1α nucleus accumulation and activation in diabetic mice." (PMID 36874012, 2023).
retinal degeneration (1 paper, 2022). Degeneration of the retina. "To confirm that the pattern of retinal degeneration seen originally in the pigmented Arap1−/− mice was still present, we sectioned eyes and stained with Hematoxylin and Eosin (H&E) to visualize retinal morphology." (PMID 35758026, 2022).
cancer (4 papers, 2012 to 2024). A tumor composed of atypical neoplastic, often pleomorphic cells that invade other tissues. "Eight genes were identified with SVs occurring in at least one cancer cat, with two genes found to impact only cancer individuals: ARAP1 and MCIDAS." (PMID 38580653, 2024). "Cancer cats Pavarti, Sushi, and Wasabi shared a coding sequence deletion 530 bp in size in ARAP1, and Wasabi, Pavarti, and Gorton shared a coding sequence deletion 1967 bp in size in MCIDAS." (PMID 38580653, 2024). "To investigate the effects of ARAP1 in LUAD, we constructed ARAP1 over-expressed (ARAP1 OE) LUAD cancer cell lines using a lentivirus system." (PMID 38008882, 2023). "qRT-PCR results showed that ARAP1 OE did not cause similar effects on RhoA/B/C mRNA expression in different LUAD cancer cells." (PMID 38008882, 2023). "We next sought to investigate whether ARAP1 regulates stress fibers formation in LUAD cancer cells." (PMID 38008882, 2023). "In summary, these results demonstrate that ARAP1 could inhibit LUAD cancer cells metastasis." (PMID 38008882, 2023). "In summary, we found that ARAP1 is frequently reduced in lung LUAD tumor tissues and cells, and displays metastatic suppression in LUAD cancer cells via inhibiting Rho GTPase-mediated microfilament remodeling." (PMID 38008882, 2023). "We further examined whether the GAP activity of ARAP1 contributes to its migratory and invasive inhibition in LUAD cancer cells." (PMID 38008882, 2023). "Therefore, we demonstrate that ARAP1 negatively regulates stress fibers formation, which would contribute to the motility and migration of LUAD cancer cells." (PMID 38008882, 2023).
tumor (2 papers, 2023). "Moreover, analysis of Kaplan–Meier survival datasets showed that lower expression of ARAP1, even in tumor tissues of early-stage, was closely associated with poorer overall survival (OS) and progression-free survival (PFS) in LUAD patients." (PMID 38008882, 2023). "aRAP1 plays a role in the invasion and metastasis of various tumor cells by regulating adhesive junctions and cytoskeletal remodeling." (PMID 36816016, 2023). "Here, we found that the expression of a GAP protein, ARAP1, is frequently reduced in tumor tissues and its downregulation is positively correlated with a worse prognosis in LUAD patients." (PMID 38008882, 2023). "The results revealed that both protein and mRNA expression of ARAP1 were frequently decreased in tumor samples as compared with the adjacent normal counterparts." (PMID 38008882, 2023). "We found that ArfGAP with RhoGAP Domain, Ankyrin Repeat and PH Domain 1 (ARAP1) mRNA is frequently reduced in tumor tissues, and its lower expression correlates with worse prognosis of patients with LUAD." (PMID 38008882, 2023). "We identified that both mRNA and protein expression of ARAP1 were reduced in LUAD tumor tissues in comparison to normal tissues." (PMID 38008882, 2023). "Here, we examined the expression of ARAP1 in a LUAD cohort, and found that ARAP1 is frequently downregulated in tumor tissues." (PMID 38008882, 2023). "To eliminate the effects of tumor heterogeneity, we also analyzed the expression of ARAP1 based on TCGA and CPTAC data, and the results further support that the expression of ARAP1 is reduced in LUAD tumor tissues." (PMID 38008882, 2023).
ARAP1 also shares sentences with these, for which no sentence is quoted: Obesity (3 papers); asthma (1); Cirrhosis (1); esophageal adenocarcinoma (1); inflammatory bowel disease (1); serous adenocarcinoma (1).